STAT3 (signal transducer and activator of transcription 3)
Diseases named in the same sentence as STAT3 in open-access papers (continued):
Sharing a sentence is not in itself a finding about the gene and the disease.
breast cancer (continued). "Compound 47 showed cytotoxic activity selectively against STAT3-dependent MDA-MB-231 breast cancer cell line (IC50 of 5.35 μM), whereas it was practically inactive towards STAT3 null A4 cancer cell line (IC50 > 100 μM against), suggesting a STAT3-specific inhibition." (PMID 35897965, 2022). "Here, in the present study, we identified the regulation of the FoxO signaling pathway via the modulation of four genes i.e. MDM2, STAT3, IGF1R, and GRM1 which could support the functioning of the PI3K-Akt and EGFR signal against breast cancer pathogenesis." (PMID 36686654, 2022). "Although a high SHOX-2 expression was correlated to enhanced migration and invasion capacities for breast cancer cells through a SHOX-2/STAT3/WASF3 axis, no relation has been established between the SHOX-2 expression and fibrinolysis." (PMID 35935486, 2022). "In addition, STAT3 was reported to be activated by inflammatory cytokines, such as IL6, IL8 and TNFα, which enhance breast cancer proliferation, invasion and metastasis through the upregulation of Twist, Snail, Slug, Vimentin and HIF-1α." (PMID 35747796, 2022). "Furthermore, silibinin crosses the BBB and impairs the activation of signal transducer and activator of transcription 3 (STAT3), which plays roles in the formation of breast cancer brain metastasis." (PMID 36551742, 2022). "Importantly, STAT3 was recently shown to be a new direct-binding target for LYC and NAR in the context of CRC and breast cancer, respectively." (PMID 36139106, 2022). "In addition, p-STAT3 is most often observed in TNBC, but can be found in all types of breast cancer." (PMID 35314590, 2022). "Other reports propose that MNX1-AS1 can directly or indirectly influence major signaling pathways including Jak/Stat3 and Akt/mTOR in breast cancer, MAPK in cervical cancer and also possibly Notch in LSCC." (PMID 36476366, 2022). "We investigated the antitumor effects of the azetidine analogs by treating human breast cancer MDA-MB-231 and MDA-MB-468 lines harboring aberrantly-active Stat3 with increasing concentrations of H105, H120, H172, or H182 for 72 h and performing CyQuant assay for viable cell numbers." (PMID 35276290, 2022). "In ER(−) breast cancer, and TNBC in particular, the regulation of STAT3 may play an important role in breast cancer treatment." (PMID 35314590, 2022). "For treatment of solid tumors, such as breast cancer, the efficacy of histone deacetylase inhibitors (HDACs) has been suggested to be limited by LIFR expression induction and the consequent pro-oncogenic activation of the JAK/STAT3 signaling pathway." (PMID 35163731, 2022). "Taken together, these results suggest that miR-155 in breast cancer cells enhances CXCL9/10/11 expression by suppressing SOCS1 expression and tilting the p-STAT1/p-STAT3 ratio, leading to the recruitment of effective T cells to the tumor site and subsequently an improved antitumor immune response." (PMID 35925680, 2022). "Besides, HDAC6 can also activate the phosphorylation of signal transducer and activator of transcription 3 on Tyr-705 and upregulate ZEB1 in MDA-MB-231 breast cancer cells to enhance EMT." (PMID 36457493, 2022). "For instance, the lncRNA TINCR may operate as a competitive endogenous RNA in human breast cancer by recruiting DNMT1 and driving carcinogenesis through the STAT3-TINCR-EGFR signaling axis." (PMID 36157234, 2022). "We also aimed to explore the involvement of JAK2/STAT3 signaling pathway and if treatment with CPT and naringenin could eventually lead to suppression of tumor growth in a mouse model of breast cancer." (PMID 35606804, 2022). "STAT3 was activated by CEMIP to facilitate for proliferation and migration of breast cancer." (PMID 35543351, 2022).
breast cancer (continued). "The STAT family was proposed as a biomarker or immune checkpoint inhibitor for prognosis prediction or therapy in various types of solid tumors, including STAT3 and STAT5A in breast cancer; STAT3, STAT5A, and STAT6 in lung cancer; and STAT3 and STAT5A in prostate cancer." (PMID 35646925, 2022). "In addition, activated STAT3 levels are known to correlate with promyelocytic leukemia (PML) gene expression in several tumor models, including breast cancer, where it acts as an upstream regulator of PML." (PMID 35562901, 2022). "Here, in the present study, we identified the diosgenin to regulate the prolactin signaling pathway via the regulation of three genes i.e., STAT3, CYP17A1, and SRC which could avoid estrogen or progestogen receptor-mediated breast cancer progression." (PMID 36686654, 2022). "A pharmacological inhibition with the STAT3 inhibitor S3I-201 was shown to block the STAT3-G9a interaction and decrease H3K9me2 marks on the miR-200c promoter, thereby inhibiting EMT, inducing autophagy, and reducing the CSC population in breast cancer." (PMID 35740522, 2022). "Also, it was shown that IL-6 activates STAT-3 signaling that enriches CSC population, and results in trastuzumab resistance in breast cancer." (PMID 35505363, 2022). "In MCF-7 breast cancer cells stimulated with PA, Nobiletin mimics the effects of CD36 knock-down, decreasing tumorsphere formation, the expression of stemness markers (SOX2, OCT4 and NANOG), STAT3 phosphorylation, and NF-kB activation." (PMID 36568966, 2022). "Moreover, NCAPG has been shown to modulate the SRC/STAT3 signaling pathway and confer resistance to trastuzumab in HER2-positive breast cancer cells." (PMID 35280743, 2022). "Moreover, OSM displayed its growth-inhibitory effects in breast cancer cell lines (MCF-7 and MDA-MB231) through activation of STAT1 and STAT3 transcription factors, as well as by modulating the mitogen-activated protein kinase kinase (MEK)/ERK pathways." (PMID 36077744, 2022). "The same miRNA was also involved in STAT3/VEGF pathway, also detected in breast cancer." (PMID 36362406, 2022). "For example, conditioned medium from IL-6-positive breast cancer cells stimulated STAT3 phosphorylation in IL-6-negative breast cancer and non-cancerous epithelial cells, while administration of anti-IL-6 antibodies abrogated these effects." (PMID 35371975, 2022). "In CSCs, the IL-6/gp130/STAT3 signaling pathway has been demonstrated to be involved in the regulation of CSC properties such as self-renewal, stemness marker expression, and tumor cell growth in prostate cancer, glioma, endometrial cancer, and breast cancer." (PMID 35565185, 2022). "IL-11 plays an essential role in breast cancer bone metastases by inducing osteoclastogenesis via JAK1/STAT3 signaling pathway independent of RANKL." (PMID 35994202, 2022). "In breast cancer, miR-375 not only inhibits the stemness of breast cancer cells, but also reduces the adriamycin resistance of adriamycin resistant MCF-7Adr cells by impeding the JAK2/STAT3 signaling pathway." (PMID 35416122, 2022). "Annexin A2, which is highly expressed in breast-cancer-derived TEX and similar to cell surface Anx II, has been reported to promote tPA-dependent angiogenesis, possibly through macrophage-mediated activation of p38MAPK, NF-κB, and STAT3 pathways." (PMID 35163380, 2022). "In addition, four genes CCND1, ESR1, STAT3, and NCOA1 were enriched for mammary neoplasms, experimental (C0024668)." (PMID 34504716, 2021). "STAT3 is a transcription factor that could activate the expression of several multi-drug resistant (MDR) genes and result in the chemoresistance of breast cancer cells." (PMID 34551797, 2021). "STAT3, particularly phosphorylated by JAK2, is one of breast cancer clinical significance." (PMID 33672756, 2021).
breast cancer (continued). "Interestingly, the findings revealed that curcumin exposure attenuated protein expression and inhibited the phosphorylation of JAK2, STAT3, STAT5, and STAT1 in Wt and GH+ breast cancer cells." (PMID 34298639, 2021). "Here, we observed that TNBC and HER2-enriched breast cancer showed significantly higher enrichment of the STAT3 activation signature, but not the TrkA activation signature, when compared to luminal samples." (PMID 34066153, 2021). "Furthermore, metformin treatment of two primary breast cancer cells MBCDF and MBCD17 downregulated mesenchymal signature genes vimentin and SNAIL and inactivated NFKB and STAT3 signaling pathways in response to IL-6." (PMID 35052372, 2021). "Col-I was shown to boost the association of DDR1 with TM4SF1, which, in turn, induced non-canonical signalling through the JAK2/STAT3 axis in dormant breast cancer cells leading to their outgrowth at multiple organ sites." (PMID 33987095, 2021). "To determine whether the STAT3–TrkA interaction occurs in breast cancer cells, we immunoprecipitated endogenous p-TrkA (Y490) from MDA-MB-468 TNBC cells, and Western blot results confirm that endogenous STAT3 co-immunoprecipitates with p-TrkA." (PMID 34066153, 2021). "In collaborative efforts, we previously developed S3I-201, an inhibitor that prevents STAT3 dimerization, and demonstrated its efficacy in treating breast cancer growth in vivo with no noted toxicities." (PMID 33526787, 2021). "By methylating STAT3, EZH2 improved cell proliferation and migration of breast cancer cells." (PMID 34335938, 2021). "Dimethyl melaleucate and three structurally related PTs, ursolic acid, 18α-glycyrrhetinic acid, and carbenoxolone suppress EGF mediated breast cancer proliferation through sustained inhibition of EGFR and its downstream effectors STAT3 and cyclin D1 in breast cancer lines." (PMID 34681605, 2021). "The reported upregulation of SHOX2 by STAT3 activation in Helicobacter pylori-infected gastric cancer cells is a cell type-specific effect given that no elevation in SHOX2 was observed in breast cancer cells following IL6-induced STAT3 activation." (PMID 34465361, 2021). "Considering the critical role of the STAT3 signaling pathway in HDGF/TKT-driven breast cancer radioresistance, we assessed the effects of Stattic treatment combined with HDGF-depletion on breast cancer radioresistance using the MDA-MB-231 cells xenograft models." (PMID 34376200, 2021). "Importantly, the combined STAT3 and TrkA activation signature was significantly enriched in triple-negative and HER2-enriched breast cancers in comparison to luminal subtypes." (PMID 34066153, 2021). "This may support our result showing that, instead of STAT3, YY1 is a more important transcription factor regulating METTL8 expression in breast cancer." (PMID 34063990, 2021). "Nevertheless, our study underscores the complexity of WASF3 transcriptional activation and provides evidence that SHOX2 and STAT3 are assembled in the same complex on the WASF3 promoter and act synergistically to promote WASF3 expression in breast cancer cells." (PMID 34465361, 2021). "In breast cancer, LINC00520 promotes the proliferation of tumor cells by regulating STAT3." (PMID 34250091, 2021). "We have successfully illustrated that targeting IL-6R could be an alternative way to suppress IL-6/STAT3 pathway in breast cancer and demonstrate the usage of TCZ could reduce tamoxifen resistance in breast cancer." (PMID 33806019, 2021). "Here, we demonstrated that EZH2 exacerbated breast cancer in non-canonical manner by methylating STAT3." (PMID 34335938, 2021). "Moreover, MDSCs have been reported to activate the STAT3 mediated inhibition of T cell expansion and Th1 polarization via the IDO manner in breast cancer." (PMID 33957948, 2021).
breast cancer (continued). "We observed that the expression of STAT3 was enhanced in breast cancer tissues compared with the non-tumor tissues." (PMID 34789263, 2021). "Therefore, in addition to the established prognostic markers (e.g., p-STAT3, HER2 and LDH) have of breast cancer, immunologically favorable biomarkers are also needed to guide the choice and administration of therapeutic strategy for breast cancer patients." (PMID 34804909, 2021). "In addition to STAT3, there are many transcription factors and miRNAs that have been closely related with the switch to EMT in breast cancer." (PMID 33506060, 2021). "Finally, we provide a schematic representation of the biological role of the trans-cellular signaling pathway involving EZH2, STAT3, exo-miR-378a-3p, exo-miR-378d, DKK3 and NUMB in the regulation of breast cancer chemoresistance." (PMID 33823894, 2021). "Previous studies have shown that the acute blockade of STAT3 and STAT5 with SH-4-54, a small-molecule inhibitor targeting the SH2 domains of these two proteins, can increase xCT expression and thus improve system XC- activity in breast cancer cells." (PMID 33968766, 2021). "GlcN decreased STAT3 activation to reduce the expression of anti-apoptosis protein, surviving, in prostate carcinoma DU145 cells; impaired the stemness of human aldehyde dehydrogenase-positive breast cancer stem cells." (PMID 34901113, 2021). "The joint administration of ganetespib and lapatinib depleted the aberrant nuclear transcription factor STAT3, a mediator of the cell cycle and apoptosis-related pathways that is probably involved in the lapatinib resistance of HER2-positive breast cancer cells." (PMID 34290605, 2021). "In 96 HER2-enriched breast cancer patients, we observed that high STAT3 activation and high JAK2-STAT3/TrkA co-activation, but not high TrkA activation, correlate with a shortened time to develop overall metastasis." (PMID 34066153, 2021). "For example, lncRNA LINC00899 suppresses breast cancer progression by inhibiting miR-425, lncRNA ZFAS1 regulates oesophageal squamous cell carcinoma cell malignant behaviours via the miR-124/STAT3 axis and lncRNA MALAT1 promotes GBM proliferation and progression by targeting the miR-199a/ZHX1 axis." (PMID 33832517, 2021). "For lung metastasis-free survival of HER2-enriched breast cancer, high STAT3 activation and high co-activation, but not TrkA activation, were associated a higher potential to develop lung metastasis." (PMID 34066153, 2021). "For HER2-enriched breast cancer (N = 96), we found that high STAT3 activation and high co-activation, but not TrkA activation, were associated with a shortened time to develop brain metastasis." (PMID 34066153, 2021). "Additionally, another study has demonstrated that phosphorylated STAT3 (p-STAT3) is a substrate of PTPRD, and that the downregulation of PTPRD enhances stemness and promotes migration and invasion via the Jak/STAT3 pathway in breast cancer." (PMID 33824475, 2021). "First, the upregulation of KMO can suppress the antitumor immune responses in patients with breast cancers, and second, with an elevated KMO expression, the activation of the kynurenine pathway, via STAT3 and pSTAT3, potentially promotes the development of tumors into more aggressive phenotypes." (PMID 34683090, 2021). "The reasons for leptin advanced the development of breast cancer may be that leptin promoted the growth and proliferation and enhanced the invasion and metastasis of breast cancer cells via activating the JAK/STAT3 and PI3K/AKT signaling pathways." (PMID 34970222, 2021). "IL-6 is a negative prognostic marker in breast cancer patients mainly due to its role in regulating STAT3 and its downstream targets promoting tumor cell proliferation, survival, and angiogenesis." (PMID 34067421, 2021). "The weak miR-124 expression could enhance STAT3 expression and promote radioresistance in HER2-positive breast cancer." (PMID 34804940, 2021).
breast cancer (continued). "Furthermore, a natural flavonoid compound, pectolinarigenin, inhibited breast cancer lung metastasis, which simultaneously enhanced the CD8+ T cells recruitment and inhibited the STAT3 phosphorylation." (PMID 33957948, 2021). "Utilizing Nluc, a phospho BRET platform has recently been developed to monitor canonical as well as non-canonical STAT3 activation in breast cancer cells." (PMID 34365218, 2021). "In mammary tumors, for example, TAMs secrete epidermal growth factor receptor (EGFR) family ligands, including heparin-binding EGF-like growth factor (HB-EGF), and activate STAT3-related signaling pathways to fuel tumor cell proliferation." (PMID 34178692, 2021). "Our study demonstrated that EZH2 exacerbates breast cancer through STAT3 signaling in non-canonical manner." (PMID 34335938, 2021). "In HER2-enriched breast cancer, high STAT3 activation and high co-activation, but not high TrkA activation, correlated with an increase potential to develop bone metastasis." (PMID 34066153, 2021). "The inflammatory cytokines/chemokines secreted by the adipose tissues in the local and/or system could activate the NF-kB, STAT3, HIF-1 and SIRT1 signaling pathways to promote invasion and metastasis of breast cancer." (PMID 34413268, 2021). "In a mouse breast cancer model, miR-19a induced the switch from the immunosuppressive M2 to the pro-inflammatory M1 TAM phenotype by targeting Fos-related antigen-1 (Fra-1) and the Fra-1/STAT3 signaling pathway and controlled tumor growth and invasion." (PMID 33924670, 2021). "In the presented study, we showed for the first time that EZH2 exacerbates breast cancer in non-canonical manner via STAT3-mediated signalings." (PMID 34335938, 2021). "Our results suggest that the PAA-induced ROS deregulated Stat3/IL-6 pathway and PAA may be a potential agent targeting breast cancer and CSCs." (PMID 33202749, 2020). "Human breast cancer cell lines (MDA-MB-231, MDA-MB-468, and MCF-7) which were stably transfected with linc00514 plasmids (linc00514-OVE) were then transfected with STAT3 siRNAs (Si-STAT3) for 48 h." (PMID 32943090, 2020). "Interestingly, adipocytes and CAAs in breast cancer stroma have been shown to induce cancer cell EMT through soluble factors such as IL-6 and leptin, both of which activate Stat3 signaling and promote cancer cell migration and invasion." (PMID 32242230, 2020). "Also, siRNA-knockdown STAT3 in CRC cells decreased mRNA levels of HK2 by reducing STAT3 recruitment to HK2 promoter, consistent with the findings in breast cancer cells." (PMID 32273843, 2020). "Signal transducer and activator of transcription 3 (STAT3) is a tumor marker for early diagnosis and the activation of its pathway is related to breast cancer aggressiveness, as it plays an important role in progression, proliferation, apoptosis, metastasis, and chemoresistance." (PMID 33138097, 2020). "Our results in this study show that tangeretin inhibits the Stat3/Sox2 signaling pathway and induces CSC death, indicating that tangeretin may be a potential natural compound targeting breast cancer." (PMID 32503228, 2020). "And although shikonin was reported to possess STAT3 inhibitory potency in human lung and breast cancer cells, its effect on STAT3 of melanoma have not been defined yet." (PMID 32536866, 2020). "In addition, the Si-STAT3 transfection reduced the relative mRNA expression of JAG1 and HES1 in linc00514-OVE breast cancer cells." (PMID 32943090, 2020).